VPS36 (vacuolar protein sorting 36 homolog)
Description:
Component of the ESCRT-II complex (endosomal sorting complex required for transport II), which is required for multivesicular body (MVB) formation and sorting of endosomal cargo proteins into MVBs. The MVB pathway mediates delivery of transmembrane proteins into the lumen of the lysosome for degradation. The ESCRT-II complex is probably involved in the recruitment of the ESCRT-III complex. Its ability to bind ubiquitin probably plays a role in endosomal sorting of ubiquitinated cargo proteins by ESCRT complexes. The ESCRT-II complex may also play a role in transcription regulation, possibly via its interaction with ELL. Binds phosphoinosides such as PtdIns(3,4,5)P3.
Synonyms: C13orf9; EAP45; CGI-145
Tractability: Antibody: the Human Protein Atlas places it where antibodies can reach. PROTAC: ubiquitination databases record sites on it; its protein half-life has been measured.
Gene: Protein-coding gene on chromosome 13 (52,412,602 to 52,450,684, reverse strand). Ensembl gene ENSG00000136100.
Subcellular location: Cytoplasm; Endosome; Late endosome; Membrane; Nucleus
Subcellular location (Human Protein Atlas): Lysosomes; Vesicles; Cell Junctions; Plasma membrane
Pathways (Reactome):
Disease: HCMV Late Events
Vesicle-mediated transport: Endosomal Sorting Complex Required For Transport (ESCRT)
Gene Ontology:
Molecular function: protein binding; ubiquitin binding; phosphatidylinositol-3-phosphate binding
Biological process: macroautophagy; membrane fission; multivesicular body assembly; protein transport to vacuole involved in ubiquitin-dependent protein catabolic process via the multivesicular body sorting pathway; endosome transport via multivesicular body sorting pathway
Cellular component: cytosol; endosome; ESCRT II complex; extracellular exosome; late endosome membrane; lysosome; plasma membrane; late endosome; cytoplasm; membrane; nucleus
Genetic constraint (gnomAD): Loss-of-function variants: 25 observed, 55.02 expected, observed/expected ratio (o/e) 0.45, 90% interval 0.33 to 0.63. The upper end of that interval is the gene's LOEUF score, 0.63, which puts it in group 2 of 6, group 1 being the genes least tolerant of losing a copy. Missense variants: 322 observed, 442.18 expected, observed/expected ratio (o/e) 0.73, 90% interval 0.66 to 0.8. Synonymous variants: 133 observed, 154.04 expected, observed/expected ratio (o/e) 0.86, 90% interval 0.75 to 1.
Homologues: Orthologues: chimpanzee VPS36 (100% identical), macaque VPS36 (99% identical), rabbit VPS36 (97% identical), rat Vps36 (96% identical), mouse Vps36 (96% identical), dog VPS36 (92% identical), pig VPS36 (91% identical), guinea pig VPS36 (85% identical), tropical clawed frog vps36 (85% identical), zebrafish vps36 (84% identical), Drosophila melanogaster Vps36 (46% identical), Caenorhabditis elegans vps-36 (42% identical).
Diseases named in the same sentence as VPS36 in open-access papers:
VPS36 is named in the same sentence as 8 diseases in open-access papers, as found by Europe PMC text mining. Sharing a sentence is not in itself a finding about the gene and the disease. The quoted sentences say what the papers report.
viral infection (2 papers, 2017 to 2019). "In the virus infection context, we observed that the downregulation of VPS36 by DsiRNAs could partially augment the viral yield." (PMID 31022991, 2019). "A better understanding of how VPS36 interfere with PEDV replication is critical not only for our overall understanding of PEDV–host interaction, but for our general knowledge of how host proteins are modulated in the face of stress triggered by viral infection." (PMID 31022991, 2019).
glioma (1 paper, 2021). A benign or malignant brain and spinal cord tumor that arises from glial cells (astrocytes, oligodendrocytes, ependymal cells). "For instance, MVB12A, VPS25, CHMP2A, and IST1 were significantly upregulated in glioma, whereas VPS36 and CHMP1B were significantly downregulated." (PMID 34863175, 2021).
prostate carcinoma (1 paper, 2021). A carcinoma that arises from epithelial cells of the prostate gland. "VPS36 are under-expressed in advanced prostate cancer and have been associated with prostate cancer cell proliferation." (PMID 34863175, 2021).
infection (7 papers, 2016 to 2025). The state of being infected such as from the introduction of a foreign agent such as serum, vaccine, antigenic substance or organism. "For example, the subset of proteins ATMCB1, VPS36, LRS1, SH3P2 and RIN2 were up-regulated during infection with S. sclerotiorum and B. cinerea, and could be novel ubiquitin- and/or AIM- binding receptors with functions in immunity." (PMID 35635102, 2022).
cancer (2 papers, 2020 to 2021). A tumor composed of atypical neoplastic, often pleomorphic cells that invade other tissues. "The finding in a 1N patient of duplicated CKAP2, THSD1, and VPS36 genes in 13q14.3 is very interesting because CKAP2 is responsible for spindle bipolarity and chromosome stability and may represent a new factor contributing to eye tissue cancer development." (PMID 32577795, 2020).
tumor (2 papers, 2009 to 2013). "Thus, this study supports the idea that de-regulation of signaling pathways, especially JNK and JAK/STAT signaling, in vps22, vps25, and vps36 mutant tissues leads to neoplasia." (PMID 23418496, 2013). "To understand this tumor-like phenotype in more detail, we examined proliferation, cellular architecture, differentiation, and metastatic potential of eye-antennal discs predominantly mutant for vps22, vps25, or vps36." (PMID 23418496, 2013). "Therefore, vps22, vps25 and vps36 mutant discs display neoplastic tumor characteristics." (PMID 19132102, 2009).
VPS36 also shares sentences with these, for which no sentence is quoted: breast carcinoma (2 papers); pancreatic cancer (1).